SNORD115-29 (small nucleolar RNA, C/D box 115-29)
Synonyms: HBII-52-29
Gene: Small nucleolar RNA gene on chromosome 15 (25,223,246 to 25,223,327, forward strand). Ensembl gene ENSG00000199704.
Gene Ontology:
Biological process: RNA processing
Cellular component: nucleolus
Homologues: Orthologues: macaque SNORD115 (99% identical). Paralogues in human: SNORD115-11 (100% identical), SNORD115-36 (100% identical), SNORD115-43 (100% identical), SNORD115-12 (99% identical), SNORD115-16 (99% identical), SNORD115-22 (99% identical), SNORD115-26 (99% identical), SNORD115-39 (99% identical), SNORD115-44 (99% identical), SNORD115-6 (99% identical), SNORD115-9 (99% identical), SNORD115-10 (98% identical), and 37 more.